IFNG (interferon gamma)
Diseases named in the same sentence as IFNG in open-access papers (continued):
Sharing a sentence is not in itself a finding about the gene and the disease.
infection (continued). "At 48 hours after initial infection, culture media was evaluated for IFNγ levels as a marker effector cell activation." (PMID 39276533, 2024). "To determine if the loss of Cd1d-restricted NKT cells would impact IFNγ production, we tested serum samples from WT and CD1d−/− mice 4 h after infection and analyzed samples for IFNγ via luminex." (PMID 39445806, 2024). "Ifnγ−/− mice were infected with 10,000 C. parvum oocysts and injected with 5-ethynyl-2-deoxyuridine (EdU) on day 8 of infection, when oocyst shedding peaks." (PMID 38995074, 2024). "Recently it was shown that in vitro certain subsets of murine and human neurons can kill intracellular parasites in response to IFNγ stimulation prior to infection." (PMID 38912206, 2024). "NK-derived IFNγ is critical for monocyte differentiation at the site of infection and IFNγ which in turn increases local production of IL12 by monocyte-derived DCs." (PMID 39445806, 2024). "JNK−/− mice are highly resistant to A. phagocytophilum infection, and this has been linked to the repressive role of JNK on CD1d-restricted natural killer T cells production of IFNγ, a cytokine that is critical for clearing the infection in mice." (PMID 38415594, 2024). "By treating HEp2 cells with 10 U/mL IFNγ for 12 hours prior to infection, we observed a stark decrease in size of chlamydial inclusions at 24 hpi, indicating a lack of growth under these conditions." (PMID 39194253, 2024). "We also tested the effect of IFNγ stimulation post infection in the murine macrophage cell line, RAW264.7." (PMID 39292011, 2024). "A detailed temporal analysis of the pro-inflammatory cytokines secreted by human PBMCs showed an increased concentration of IL-1β, IL-6 and TNFα starting at 4 h post-infection, with IFNγ amounts rising at 8 h post-infection." (PMID 38793740, 2024). "An early study reported that NK cells were recruited to the female genital tracts of mice as early as 12 h post-infection with C. muridarum, and that depletion of NK cells resulted in reduced IFNγ and a Th2-skewed immune response." (PMID 39203989, 2024). "Our results show a significant decrease in IL-1β (p = 0.004), IL-8 (p = 0.01), IL-12 (p < 0.0001), and IFNγ (p = 0.006) at 5 days post infection in the presence of 0.5% Aq." (PMID 38790647, 2024). "Subsequently, we passed this pool of parasite mutants an additional four times, this time in HFFs that were either infected and left unstimulated or infected and stimulated with IFNγ 4 h post infection." (PMID 39292011, 2024). "As we saw in other infections with live 106 tachyzoites, we observed significantly higher (P < 0.05) IFNγ levels in N. caninum compared to T. gondii." (PMID 39445806, 2024). "Although IFNβ plays an important role in the antiviral pathway, it promotes the survival of MTB in its infection, probably because of its ability to inhibit the antimycobacterial effect produced by IFNγ and enhance mycobacterial virulence." (PMID 39313213, 2024). "After the initial week following infection, adaptive immunity takes on the responsibility of producing IFNγ." (PMID 39065071, 2024). "In WT mice, NK cells represented ~60% of all IFNγ-producing leukocytes during infection and the decreases in IFNγ-producing NK cells in Ifne-/- mice correspond with reductions in the total numbers of IFNγ-producing leukocytes (Fig. EV2G)." (PMID 38263527, 2024). "An attempt to document infection incidence in adolescents using serial interferon gamma release assays (IGRA) is planned in the same community as that in which we undertook our TST survey." (PMID 38889188, 2024). "Among all the immune cells examined in the BAL, neutrophils were the predominant source of IFNγ after infection." (PMID 38295799, 2024). "IFNγ production by PPD-stimulated peripheral blood mononuclear cells peaked at day 7 post-infection, remaining significantly above baseline concentrations up to day 84 (aerosol group) and day 168 (intradermal group; appendix pp 4, 17, 29)." (PMID 38621405, 2024).
infection (continued). "At 10 days post infection, the expression of IL-1β (p = 0.005), IL-8 (p = 0.0002), IL-12 (p = 0.0003), and IFNγ (p = 0.006) was also significantly affected." (PMID 38790647, 2024). "We found that NPFF inhibited infection-induced BAL IFNγ+ neutrophils, and reduced the frequency of ROS+ neutrophils, but not in Mrgpra1−/− mice." (PMID 38295799, 2024). "In contrast to the robust response seen with LCMV, RRV-gp33 infection induced tenfold lower levels of IFNγ and TNF producing CD8+ T cells after peptide restimulation, and GrB expression was apparent in only 5% of DLN CD8+ T cells at 5 dpi." (PMID 39535221, 2024). "This blockade of type I IFN signaling resulted in greater CD8+ T-cell responses in the DLN at day 5 after RRV-gp33 infection, such that the number of gp33-specific, IFNγ+, TNF+, and GrB+ CD8+ T cells after RRV infection now matched those of LCMV infection." (PMID 39535221, 2024). "In contrast, IFNγ responses were prominent in all three compartments after vaccination and infection, and were durable until 10 weeks post-infection when the mice had largely cleared the infection." (PMID 38712080, 2024). "In mice, CD8+ T cells were found to be important in maintaining stable latent phase of infection, in part through production of IFNγ." (PMID 39717773, 2024). "Although the role of CD27+ IFNγ-producing γδ T cells in infection and cancer is well established, the biology of these cells during disease and their adaptation to foreign insult remain poorly elucidated." (PMID 38816652, 2024). "In an infection model, the production of cytokines like IFNγ has been found to lead to better outcomes in terms of infection progression." (PMID 38542999, 2024). "Our study reveals that T. gondii depends on the MYR translocon complex to prevent parasite premature egress and host cell death in human cells stimulated with IFNγ post-infection, a unique phenotype observed in various human cell lines but not in murine cells." (PMID 39292011, 2024). "This cytokine is essential for NK cell development and survival, and contributes to their recruitment, expansion, activation, and IFNγ production during infection." (PMID 38263527, 2024). "Prior studies using murine models using different Ehrlichia species pathogens reported that CD4+ T cell-mediated IFNγ production is essential for mitigating a fatal outcome from an infection." (PMID 39204029, 2024). "Hepatic expression of the proinflammatory cytokines Tnfα, Ifnγ, and Il12 increased with infection and decreased with the host’s age at the time of infection." (PMID 39404406, 2024). "At 72 h post‐infection, these cytokine/chemokine levels shifted with significantly lower IFNγ and IL‐4, significantly higher IL‐5, IL‐10, IL‐17a, and CCL‐5/RANTES, and comparable IL‐2 and TNFα levels." (PMID 37990641, 2024). "All but THP-1 cells showed a significant increase in LDH release driven by the early egress phenotype following infection and IFNγ treatment." (PMID 39292011, 2024). "Deucravacitinib is a potent Type I IFN inhibitor and indirectly inhibits IFNγ; however, infection rates are low relative to JAK1,2,3 inhibitors due to optimized dosing that sufficiently controls inflammation without complete pathway inhibition." (PMID 39403378, 2024). "In vitro infection of splenocytes with Burkholderia pseudomallei bacteria results in rapid expression of IFNγ in CD8 CD44hi (activated/memory) compared to naive CD8 CD44lo cells." (PMID 39669576, 2024). "After 7 days of infection, the levels of Th1 cytokines IFNγ, IL-6, and TNFα were elevated in the BALF, but these levels were significantly reduced in TLR7 KO mice." (PMID 39769461, 2024). "(G) Quantification of RNF213 localizing to Ct inclusions during infection of unprimed and IFNγ-primed (100 U/mL) A549 cells at 24 hours post infection." (PMID 38358795, 2024). "In both mice and humans, type II interferon-γ (IFNγ) is essential for the immune control of T. gondii during both acute and chronic phases of infection." (PMID 39292011, 2024).
infection (continued). "Vγ6Vδ1 T cells, in specific, play a protective role during infection and produce IFNγ along with IL-17." (PMID 38397462, 2024). "TNFα and IL-6 were significantly raised in right vagotomized mice at days 3 and 8 post-infection, respectively, and left vagotomized mice showed an increase in IFNγ at day 8 post-infection." (PMID 38626267, 2024). "In our current study, we uncover that T. gondii depends on the MYR translocon complex to prevent premature egress and host cell death in human cells stimulated with IFNγ post infection." (PMID 39292011, 2024). "(F) Representative images of RNF213 localizing to inclusions of WT Ct, garD::GII, and cdu1::GII strains during infection of A549 cells primed with IFNγ (100 U/mL)." (PMID 38358795, 2024). "STAT4 is the transcription factor that is activated in response to IL-12 and IFNγ and stimulates Th1-mediated host protective responses during the infection." (PMID 38809023, 2024). "The infection induced an increase of the gene expression of the chemokine CCL5 and the cytokine IFNγ (approximately 250 times) in the IPP of lambs during the resolution of infection, which we also observed in the distal jejunum and JPP." (PMID 38756777, 2024). "Th1 immune responses, in particular interferon-gamma (IFNɣ) production, are characteristics of silent infections, occur very early after infection, and can effectively contain MAP infections." (PMID 38167436, 2024). "Among the cytokine promoters evaluated, the most substantial methylation differences at each tissue site during SIV infection compared to infection-naïve animals were observed at the IFNγ promoter of CD8+ T cells." (PMID 39772149, 2024). "The number of IFNγ-producing T cells increased in most vaccinated dogs following the infection challenge." (PMID 39204029, 2024). "A significantly increased expression of IFNG was noticed in the Mtb-infected lungs at 2 and 4 weeks post infection, compared to the uninfected controls." (PMID 38338937, 2024). "Multiplex analysis revealed substantial cytokine and chemokine levels in lung homogenates 3 weeks post infection, dominated by a strong IFNγ response." (PMID 39737195, 2024). "Gene-knockout, antibody depletion, and adoptive transfer studies in mice indicate Th1 cells and their defining production of IFNγ are key mediators for resolving primary infections." (PMID 39203989, 2024). "IFNγ is upregulated during an infection and is mainly secreted by Th1 and CD8+ cytotoxic lymphocytes, natural killer cells and other antigen presenting cells." (PMID 39622178, 2024). "The infection-dependent potentiation of IL-18 release from both untreated and IFNγ-primed cells was statistically significant." (PMID 39254346, 2024). "In these experiments, we subjected naïve HFFs to IFNγ stimulation 4 h after infection with WT, ∆myr1, or ∆myr1::MYR1 complemented parasites and subsequently assessed them via immunofluorescence analysis 26 h post-infection." (PMID 39292011, 2024). "In vitro studies of Chlamydia-infected epithelial cells demonstrated growth inhibition and development of enlarged aberrant chlamydial forms when exposed to high concentrations of IFNγ throughout infection." (PMID 39194253, 2024). "Antigen-specific IFNγ responses induced following vaccination and infection correlate with enhanced antifungal activity." (PMID 38712080, 2024). "We recently showed that T. gondii and N. caninum grow similarly in mice during the first 24 h post-infection, but only N. caninum induces an IFNγ-driven response within hours that controls the infection." (PMID 39445806, 2024). "In contrast, higher levels of pro-inflammatory factors like IL-6, GM-CSF and CXCL1 were observed in BALF along with lower amounts of IFNγ and IFNγ-producing T-cells one day post-infection." (PMID 39472590, 2024). "Our data indicate that while the IFNγ-producing cells are likely the same for these responses (NK cells), they respond differently to infection and antigen preparations from N. caninum." (PMID 39445806, 2024).
infection (continued). "Our previous data show that IFNγ fuels the infection of mouse and human astrocytes by T. cruzi via autocrine TNF production." (PMID 38776344, 2024). "We measured the IFN induction levels in the mouse lungs by extracting total RNA from homogenized lung tissue at 1 day post-infection, and performed qRT-PCR to detect IFNα1, IFNβ, IFNγ, and IFNλ3 expression levels." (PMID 38315735, 2024). "Interferon-gamma in poultry is a proinflammatory cytokine that is involved in the host defense against infection." (PMID 39687852, 2024). "Consistent with this, the expression of both IFNβ and IFNγ declined by 50% from day 14 to day 28, which suggests a resolving infection." (PMID 39000027, 2024). "Cells infected with the ∆myr1 mutants and treated solely with Compound 1 exhibited only 10% cell death, while infection with WT or ∆myr1::MYR1 showed less than 10% cell death upon treatment with Compound 1 alone or in combination with IFNγ." (PMID 39292011, 2024). "We find that at both steady state and during infection, distinct populations of neutrophils express NPFF and IFNγ which are associated with divergent polarized states." (PMID 38295799, 2024). "C57BL/6 mice infected with L. major mice are resistant to infection, triggering a robust Th1 response, which is aligned with the pro-inflammatory M1 phenotype (interferon-gamma (IFN-γ) and interleukin-12 (IL-12) production)." (PMID 39211053, 2024). "T. gondii employs TgIST in conjunction with GRA16, GRA28, and GRA24 to suppress the IFNγ response and inhibit premature egress during acute stages of infection." (PMID 39292011, 2024). "We generally observed similar T-cell response kinetics—in terms of IFNγ responses over time—in the lung, spleen, and blood after the booster infection." (PMID 38675801, 2024). "The IFNγ-dependent clearance corresponded with decreased number of PV and parasites per vacuole by 14 h post-infection (hpi)." (PMID 38538595, 2024). "The severity of toxoplasma infection in mice is determined by the ability of the parasite to counteract the host’s resistance to infection, which appears to be targeted at interferon-gamma (IFN-γ) through its parasite kinase." (PMID 39061995, 2024). "In human leprosy, intradermal IFNγ administration can alter local infections from lepromatous to tuberculoid leprosy, increasing the numbers of CD4+ cells and reducing bacterial numbers in dermal biopsies." (PMID 38543472, 2024). "Methylation at the IFNγ promoter declined (p = 0.0118) in all 4 animals post- compared with pre-infection." (PMID 39772149, 2024). "This absence of NK cells is associated with reduced total numbers of IFNγ-producing leukocytes (Fig. EV5E) and Ifng transcript levels in the upper FRT during infection." (PMID 38263527, 2024). "It is also reported that mutations within STAT1 which is an essential downstream factor in IFNα/β and IFNγ signaling pathways leads to lethal outcomes from infection with HSV-1, HCMV, and Epstein-Barr virus." (PMID 39352890, 2024). "Th cells subsequently migrate to the site of infection, secreting cytokines like interferon-gamma (IFN-γ), which enhance macrophage activation by promoting phagosome-lysosome fusion and the production of reactive nitrogen and oxygen species." (PMID 39421098, 2024). "Analysis of serum cytokines 8 weeks post-challenge of control and vaccinated mice indicated that infection by Mtb induced production of IL-27, in addition to inflammatory cytokines IL-17 and IFNγ." (PMID 38390338, 2024). "ICVB-1042 infection of A375-Luc2 cells led to a significant increase in IFNγ and IL-2 production by allogeneic PBMCs." (PMID 39271928, 2024). "While TgPHYaKOII mutant parasites can establish an infection in the gut, they are unable to efficiently disseminate to peripheral tissues because TgPHYa is required to resist IFNγ-triggered killing and does so by overcoming IDO scavenging of tryptophan." (PMID 38857298, 2024).
infection (continued). "The chronic upregulation of both IL10 and IFNG together indicates recognition of the immune system of infection status but demonstrates an inappropriate response of immune activation." (PMID 39766767, 2024). "In this pilot study, nasal swab samples from 75 rhinoceros with defined infection status based on M. bovis antigen-specific interferon gamma release assay (IGRA) results were analysed by GeneXpert MTB/RIF Ultra, BACTEC MGIT and TiKa–MGIT culture." (PMID 38172248, 2024). "To test if the early egress phenotype of Δmyr1 mutants was exclusive to primary fibroblasts or occurred in other human cell lines, we examined LDH release upon infection with Δmyr1 mutants followed by IFNγ treatment." (PMID 39292011, 2024). "During tissue injury and infection, M1 macrophages develop in response to interferon γ (IFNγ) and microbial products such as lipopolysaccharide (LPS)." (PMID 39622178, 2024). "From mouse models, IFNγ inhibits VZV replication in a cell line‐dependent manner via VZV gene expression inhibition after the immediate early stage of infection." (PMID 38317404, 2024). "Given the requirement of CD4+ T cells and the central role of the spleen in the clearance of B. microti, we sought to clarify the role of IFNγ secreted by CD4+ T cells on activated splenic macrophages in optimal clearance of the infection." (PMID 39452729, 2024). "Our transcriptomic profiling and biological processes analysis explored that H1N1pdms-induced dysregulated genes were mainly involved in defence to infection, chemokine receptors binding chemokines, and regulating of IFNG signalling." (PMID 38229736, 2024). "Similar to our findings, there were mid-infection increases in circulating cytokines, IL-6, IL-12 and IFNγ with peak levels at day 14 post- inoculation for IL-12, day 21 for IFNγ and day 28 for IL-6." (PMID 36893126, 2023). "Ex vivo bone marrow-derived macrophages were differentiated into classically activated macrophages through IFNG activation and infection with Leishmania infantum." (PMID 37235312, 2023). "Fifth, limited cell numbers were available for scRNA-seq, limiting our ability to discern the origins of newly detected IFNG+ spike-specific CD8+ T cell clonotypes after infection or subsequent vaccination." (PMID 38064569, 2023). "During an infection with Toxoplasma gondii, the host immune response stimulates the production of different molecules, such as interferon gamma (IFNγ), tumor necrosis factor (TNFα), and nitric oxide." (PMID 38004683, 2023). "In this work, we describe the unexpected role of TgLOXL1 during mouse infection, the cytokine response from wild-type (WT) and IFNγ KO mice as well as the localization of TgLOXL1 within the parasite and immune cells." (PMID 37646522, 2023). "In the fetal amniotic fluid, infection with either Pru or RH induced high levels of IFNγ, IFNβ, IL‐1β, and IL‐10 as compared to saline controls." (PMID 37259639, 2023). "In this study, we applied the oncolytic recombinant NDV (rNDV) to induce cell-mediated immunity in treated patients and succeeded to achieve the oncolytic activity together with the production of canine IFNγ by rNDV-cIFNγ infection." (PMID 37022566, 2023). "Our data show that infection of IFNγ-stimulated HFFs with parasites in which these GRA32-like proteins were knocked out led to significantly more host cell death compared to infection with wild-type parasites." (PMID 36916910, 2023). "Interferon-gamma in poultry is an essential cytokine in host defense against pathogens, as demonstrated in various infection models." (PMID 37041838, 2023). "In contrast, stimulation of unpolarised macrophages with IFNγ after establishment of infection significantly increased Salmonella CFU over time." (PMID 37190073, 2023). "We found that infection with Mycobacterium avium impacts bone turnover by decreasing bone formation and increasing bone resorption, in an IFNγ- and TNFα-dependent manner." (PMID 37153579, 2023).